HIF1A (hypoxia inducible factor 1 subunit alpha)
Diseases named in the same sentence as HIF1A in open-access papers (continued):
Sharing a sentence is not in itself a finding about the gene and the disease.
kidney disease (continued). "HIF-1α is involved in the pathogenesis of kidney diseases, as are PAI-1 and CTGF." (PMID 27678081, 2016). "However, the functions of HIF-1α CTAD in kidney diseases remain uncertain." (PMID 37225700, 2023). "However, the precise role of HIF-1α CTAD in hypoxic kidney diseases is not well understood." (PMID 37225700, 2023). "Recent studies have also shown that in hypoxic kidney disease models, miR-210 targets HIF-1α and inhibits the activation of downstream target genes of HIF-1α following severe hypoxia, mitigating hypoxia-induced apoptosis." (PMID 40469714, 2025). "Although the roles of HIF-1α NTAD in kidney diseases have been recognized, the exact effects of HIF-1α CTAD in kidney diseases are poorly understood." (PMID 37225700, 2023). "Several studies reported that hypoxia mimetics induced preferentially HIF-2α activation, thus acting less on HIF-1α or even suppressing HIF-1α activation showing a mutual antagonism of HIF isoforms in cardiac, vascular and renal disorders." (PMID 35327980, 2022). "As a class of small single-stranded noncoding RNA, miR-34a is involved in the pathological process of various diseases such as dietetic kidney disease by regulating the function of target genes such as Egr1, GAS1, and Sirt1/HIF-1α." (PMID 36345369, 2022). "Interestingly, their overexpression could ameliorate renal disease by inhibiting HIF-1α." (PMID 32085620, 2020). "Hypoxia-inducible factor-1 (HIF-1), composed of HIF-1α with HIF-1β, is thought to play a role in kidney disease." (PMID 32028746, 2020). "Additionally, 71 pathways were found to be commonly enriched, including HIF-1α, VEGF, PI3K-Akt, mTOR, Rap1, PPAR, FcγR-mediated phagocytosis, T cell receptor, and regulation of actin cytoskeleton, which are related to kidney diseases." (PMID 40356949, 2025). "Thus, HIF-1α overexpression in mesangial cells of diabetic kidneys, compared to the limited expression of HIF-2α, aids the progression of kidney disease." (PMID 39648258, 2025). "Since hypoxia has been cited as a driver of kidney disease in the TI32, and a hypoxic microenvironment may result in decreased oxidative metabolism, we examined the contribution of HIF1A to metabolic gene signatures." (PMID 34285256, 2021). "So, combined activation of HIF-1α and HIF-2α may raise a concern regarding undesired complications, such as angiogenesis and worsening kidney disease." (PMID 30108502, 2018). "This review summarizes the mechanisms of HIF-1α regulation in animal models of renal disease, which not only provides new insight with regard to understanding the pathophysiology of kidney disease, but also provides rational strategies for therapeutic intervention." (PMID 36364144, 2022). "The upregulation of HIF-1α may contribute to the protective effects of SGLT2 inhibitors on blood pressure, and empagliflozin exerts anti-inflammatory action in nondiabetic kidney disease as well." (PMID 31537914, 2019).
kidney (37 papers, 2005 to 2026). "This is consistent with our previous report showing that the alcoholic fatty liver is worsened in Hif-1α-deficient mice." (PMID 30242180, 2018). "Materials and Methods: We retrospectively evaluated microvessel density (MVD) by CD34 immunohistochemical (IHC) staining and hypoxia by IHC staining for Hypoxia-inducible factor 1α (HIF-1α), comparing right- and left-lung parenchyma in 53 lung NETs." (PMID 36233825, 2022). "Since our study mimicked the acute kidney injury setting and involved a short period (2 h after resuscitation) of recovery after hemorrhage and kidney injury, HIF-1α was a suitable candidate to study the effect of centhaquine resuscitation in these animals." (PMID 34012389, 2021). "Upregulation of mTOR and its downstream target gene p70S6K, which in turn activates HIF-1α, exacerbates ischemia/reperfusion-induced liver inflammation." (PMID 32719658, 2020). "To investigate the significance of HIF-1α during colorectal carcinogenesis and progression we examined its expression in precursor lesions constituting the conventional and serrated pathways, as well as in non-metastatic and metastatic adenocarcinomas." (PMID 18983642, 2008). "We conclude that HIF-1α expression occurs in early stages in the classical and serrated pathway of colorectal carcinogenesis and achieves a maximum in the invasive stage, independent of the metastatic status of the primary tumor." (PMID 18983642, 2008). "In the current study, we presented a comprehensive meta-analysis for 12 polymorphisms in four VEGF/hypoxia/angiogenesis pathway genes (VEGF, HIF1α, eNOS, and HRAS) including 96 case-control studies to examine the precise associations between these polymorphisms and risk of urogenital neoplasms." (PMID 29942264, 2018). "Therefore, although up-regulation of HIF-1α is protective in acute kidney injury, the long-term HIF-1α activation is injurious in CKD18,19,23,25–27." (PMID 29158549, 2017). "In this study, we investigated whether HIF-1α-modified adipose-derived stem cells (ASCs) had an enhanced protective effect on cisplatin-induced kidney injury in vivo." (PMID 26044673, 2015). "Inhibition of HIF-1α by 2ME2 attenuates alveolar-capillary barrier disruption and lung edema." (PMID 25120621, 2014). "Our findings suggested that the HIF-1α CTAD-HK2 pathway represents a novel mechanism of kidney response to hypoxia, which provides a promising therapeutic strategy for hypoxia-induced kidney injury." (PMID 37225700, 2023). "In a mouse model for middle cerebral artery occlusion, astrocyte activation was shown to play a crucial role in ischemic tolerance, which is mediated through P2X7 receptor-activated HIF-1α upregulation." (PMID 31381576, 2019). "Thus, the eight gene panel (CXCL12, CK7, CDH1, CTNNB1, CD44v6, MUC16, TGFBR2 and HIF1A) can be a highly significant predictor of liver metastasis outcome independent of the standard prognostic criteria." (PMID 30383826, 2018). "Lymph node negative patients lacking HIF-1α may be considered for adjuvant radiotherapy when these results can be confirmed in independent studies." (PMID 16035955, 2005).
metabolic disorders (37 papers, 2011 to 2025). "In conclusion, the WWOX/HIF1A axis downregulation alters glucose metabolism and probably predispose to metabolic disorders." (PMID 35328751, 2022). "Recent reports indicate that the hypoxia-induced factor (HIF1α) and the Warburg effect play an initiating role in glucotoxicity, which underlies disorders in metabolic diseases." (PMID 35328751, 2022). "Acute hypoxia exposure caused metabolic disorders in these organs with high HIF-1α expression, and the liver, kidney, and brain had distinct metabolic profiles but a consistent change in glutamate." (PMID 34201416, 2021). "HIF1A is a master transcriptional regulator of genes encoding factors that govern lipid metabolism and inflammation, both of which are central mechanisms underlying the progression of metabolic disease." (PMID 32134946, 2020). "As the most mitochondria-rich tissue, the myocardium undergoes significant metabolic changes in metabolic diseases, where dysregulated oxygen sensing pathways and HIF-1α expression contribute to metabolic dysfunction and myocardial injury." (PMID 39920720, 2025). "This will help to establish a complete mechanistic framework for the cardioprotective effects of FG-4592 through stabilisation of HIF-1α and validate its applicability in different models of metabolic disease." (PMID 39920720, 2025). "HIF-1α plays a major role in regulating metabolism and influences metabolic diseases such as obesity." (PMID 39900792, 2025). "It has been recently reported that fructose metabolism and hypoxia-inducible factor-1alpha (HIF1α) pathways are connected, affecting the development of various metabolic disorders." (PMID 38276547, 2024). "The current findings highlight the importance of exploring the role of RES in the regulation of KLF7 and HIF1A expression and its potential implications for managing inflammatory diseases and metabolic disorders." (PMID 38212345, 2024). "It is shown that ROS regulates HIF-1α transcription and translation by inducing miR-21 activation of the PI3K/AKT and ERK pathways, which are linked to metabolic disorders and inflammation." (PMID 36829789, 2023). "As nicely outlined in a quite recent authoritative review, the focus on HIFs and metabolic diseases has led to the acquisition of a number of major critical concepts that have also started to discriminate the sometimes alternative roles of HIF-1α and HIF-2α." (PMID 34359934, 2021). "Previous studies have demonstrated that the upregulation of HIF-1α leads to a shift in cell metabolism under hypoxic conditions, and metabolic disorders are involved in the development of hypoxic diseases." (PMID 34201416, 2021). "In this literature review, we summarize the current knowledge about HIF-1α in OSA in relation to the possible pathways in which they contribute to metabolic disorders." (PMID 33013447, 2020). "Moreover, targeted regulation of HIF1α/BMAL1 are potential nutritional approach in reducing metabolic disorders in various mammary gland disorders in dairy animals." (PMID 40307878, 2025). "In terms of metabolism and metabolic disease, the role of HIF1α has been well-established in the regulation of sterile inflammation, tissue fibrosis, insulin action, and lipid handling in various peripheral metabolic organs/tissues including liver, intestine, pancreatic β-cell, and adipose tissue." (PMID 38509584, 2024). "Using targeted and untargeted metabolomic analysis, we discovered that GPS regulated EPA and DHA to improve metabolic disorders through activation of the PPARα pathway, and L-serine and glycine to inhibit inflammation and oxidative stress through suppression of the HIF-1α pathway." (PMID 38515850, 2024). "HIF1A is one of the master regulators of the cellular response to hypoxia, which has been proposed as one of the key reasons for adipose tissue dysfunction in obese individuals and the resulting inflammation and metabolic disorders." (PMID 36414820, 2023).
metabolic disorders (continued). "Thus it is assumed that hypoxia-inducible factor HIF1α and related bioenergetics changes (Warburg effect) play an initiating role in glucotoxicity of metabolic disorders." (PMID 35328751, 2022). "HIF-1α plays an important role in metabolic disorders and inflammation." (PMID 33993883, 2021). "Recently, Liver-specific HIF-1α knock-out revealed the importance of HIF-1α in metabolic diseases." (PMID 26098428, 2015). "Importantly, LCar and LW6 administration could improve iBAT thermogenesis of aging mice via regulating ACar metabolism, suggesting that the Sirt3/HIF1α axis and ACar metabolism in BACs might be a potential therapeutic target for aging related metabolic disorder." (PMID 39348266, 2024). "In summary, HIF-1α protected against IVDD, possibly through reducing ROS production in the mitochondria and consequent inhibition of inflammation, metabolism disorders and apoptosis of MNPCs, which provided a potential therapeutic instrument for the treatment of IVDD diseases." (PMID 36064808, 2023). "Neither hypercaloric diet intake nor CSN resection changed HIF-1α-positive staining in the CBs, suggesting that hypoxia did not play a role in stimulating the CBs in metabolic disease." (PMID 35600301, 2022).
retinopathy (30 papers, 2012 to 2025). "The degree of retinopathy was correlated to the HIF-1A Pro582Ser polymorphism." (PMID 31214621, 2019). "H2 protected retina against retinopathy of OIR mice via dual-directional regulation of HIF-1α-VEGF pathway both in hyperoxic and hypoxic phases." (PMID 38915069, 2024). "It has also been reported that pharmacological inhibition of PHDs and the subsequent stabilization of HIF1-α can prevent retinopathy in preterm infants." (PMID 37686717, 2023). "In the oxygen-induced retinopathy mouse model, rapid but transient accumulation of Hif-1α, but delayed and sustained accumulation of Hif-2α." (PMID 36147561, 2022). "Retinal HIF-1α expression increased in a murine model of oxygen-induced retinopathy and its expression decreased by treatment of fenofibric acid, an active form of fenofibrate." (PMID 33799938, 2021). "Proliferative retinopathies are characterized by hypoxia-induced pathological neovascularization driven by the HIF-1α and HIF-2α pathways." (PMID 28928465, 2017). "Previously, increased levels of HIF-1α were observed in the ischemic retinas of the retinopathy mouse model, and HIF-1α expression was correlated with VEGF expression." (PMID 25891515, 2015). "Our previous studies confirmed that K5 reduced the HIF-1α levels in the retina of retinopathy model and the retinal capillary endothelial cells." (PMID 23300882, 2012). "Thus, in diseased hypoxic retinal cells, expression of TRAP1 is induced to close mPTPs and maintain mitochondrial calcium storage, which is essential for activation of HIF1α and development of retinopathy." (PMID 37983591, 2024). "HIF-1a has a role in the stability of retina homeostasis, but intense fluctuations in carbohydrate metabolism can cause HIF-1a to fluctuate, which results in abnormal blood vessel outgrowth and progression of retinopathy." (PMID 37446104, 2023). "Hence, the current work investigated the association of HIF-1α rs11549465 and VEGF rs3025039 genetic variants with the different stages of retinopathy among T2DM Egyptian patients." (PMID 35969320, 2022). "In addition, the association of these SNPs with the levels of AGEP, VCAM-1, HIF-1α, VEGF, and CTRP3 in serum was investigated to understand their effects on the progression of retinopathy among diabetic patients." (PMID 35969320, 2022). "Moreover, in a mouse model of OIR, β-AR blockade with non-selective antagonist propanol reduced the hypoxia-upregulated VEGF and decreased the HIF-1α levels, ameliorating the retinopathy score." (PMID 35011613, 2021). "Here the authors show that adenosine receptor A2A drives pathological angiogenesis in the oxygen-induced retinopathy mouse model by promoting glycolysis in endothelial cells via the ERK/Akt/HIF-1α pathway, thereby suggesting new therapeutic targets for disease treatment." (PMID 28928465, 2017). "We examined whether HIF-1α could be induced in our murine model of light-induced retinopathy." (PMID 38536853, 2024). "The intravitreal injection of miR-18a-5p mimic in a mouse model of oxygen-induced retinopathy effectively suppressed retinal neovascularization by targeting key pro-angiogenic factors, FGF1 and HIF1A." (PMID 40002813, 2025). "The degree of retinopathy was evaluated by staining retinal sections with hematoxylin and eosin, and the expression of CCN1, HIF-1α, VEGF, caspase-3, Bcl-2, IL-1β, and TNF-α protein was analyzed by Western blotting and immunohistochemistry." (PMID 35445044, 2022). "Despite these limitations, our findings indicated that the HIF1A and IGFBP3 genes could be used to confirm retinopathy disease progression in patients with DM." (PMID 40377287, 2025). "In PPARα knockout mice, fenofibric acid treatment could not reduce upregulated expression of HIF-1α in the ischemic retina of oxygen-induced retinopathy." (PMID 33799938, 2021).
retinopathy (continued). "The present study aimed to investigate whether SPN can prevent hypoxia-induced retinal neovascularization via inhibition of HIF-1α/VEGF signaling pathway in a VEGFA secretion model of ARPE-19 cells induced by CoCl2 in vitro and a neovascularization rat model of oxygen-induced retinopathy in vivo." (PMID 28009852, 2016).
neurodegenerative disease (29 papers, 2016 to 2025). A disorder of the central nervous system characterized by gradual and progressive loss of neural tissue and neurologic function. "Specifically, Hif1a is crucial for microglial activation and directly linked to neurodegenerative disease progression." (PMID 39907554, 2025). "Inhibition of HIF-1α associated glycolysis could prevent neurodegenerative diseases, and protect the structure and permeability of the BBB; this could be through the suppression of HMGB1/TLR4/NF-κB signaling pathway-mediated neutrophil infiltration." (PMID 36834484, 2023). "The identification of HIF-1α as a transcriptional factor regulating ECM gene expression may provide a shared molecular mechanism of ECM perturbation across neurodegenerative diseases and their major risk factor, aging." (PMID 37108212, 2023). "This study not only reveals the complex regulation of HIF-1α by heavy metal pollution but also explains the possible role of HIF-1α in the development of neurodegenerative diseases." (PMID 40277555, 2025). "The second avenue is to utilize agmatine as a drug targeting HIF‐1α in the context of the role of HIF‐1α in neurodegenerative diseases." (PMID 39888089, 2025). "Numerous evidence also indicated that PARP1, SCD, AR, ALOX5, HIF1A are critical involved in HD or neurodegenerative diseases." (PMID 38918688, 2024). "In this context, experimental and clinical evidence suggested that Th17 and HIF-1α are involved in the genesis of autoimmune and neurodegenerative diseases, contributing to the persistent pro-inflammatory state." (PMID 36834484, 2023). "Research has shown that HIF-1α modulates the oxidative stress response during the progress of neurodegenerative diseases." (PMID 36674945, 2023). "Increased plasma bilirubin and beta-hydroxybutyrate, and the activation of the HIF-1α pathway are beneficial also for neurodegenerative diseases." (PMID 36552529, 2022). "In fact, HIF-1α has been proposed as a potential target for neurodegenerative diseases, since it regulates the expression of a broad range of genes that facilitate cellular adaptation to low-oxygen conditions." (PMID 34336097, 2021). "In fact, targeted induction of moderate HIF-1α levels has neuroprotective benefits in experimental models of neurodegenerative disease." (PMID 34439955, 2021). "Moreover, compelling studies have provided evidence of a protective role for HIF-1α in neurodegenerative diseases like AD." (PMID 39086755, 2024). "This indicates that HIF-1α might not only serve as a potential target for AD drugs but also potentially plays a direct protective role to AD and other neurodegenerative disease." (PMID 39086755, 2024). "Hypoxia, neuroinflammation, and ECM dysregulation are all common themes in neurodegenerative disease, and it is possible that HIF-1α transcriptional activity could be a common mediator of the changes in the ECM in these conditions." (PMID 37108212, 2023). "Due to the existing relation between Th17, HIF-1α and inflammation in neurodegenerative diseases, new therapeutic targets have been developed that could be used in the treatment of diseases with neuroinflammation." (PMID 36834484, 2023). "Emerging evidence has also shown that HIF-1α could be a potential therapeutic target for neurodegenerative diseases." (PMID 34445342, 2021). "Recent evidence suggests that regulating HIF-1α may ameliorate the cellular damage in neurodegenerative diseases." (PMID 34439955, 2021). "LA is used clinically to treat AD, but the growing knowledge we provide on glucose metabolism restoration by LA via the BDNF/TrkB/HIF-1α pathway in AD may support a novel therapy target for neurodegenerative diseases." (PMID 32973490, 2020). "Furthermore, previous studies revealed that the HIF-1α/Notch signaling pathway plays an important role in anoxic pathological processes that occur in tumors and neurodegenerative diseases." (PMID 32723315, 2020).